NOTCH1 (notch receptor 1)
Diseases named in the same sentence as NOTCH1 in open-access papers (continued):
Sharing a sentence is not in itself a finding about the gene and the disease.
tumor (continued). "Other findings reflective of CS1’s higher tumor grade and more aggressive behavior compared with CDS11 cells include the significantly higher mRNA levels of INSULINR, IGF2R, IRS1, NOTCH1, JAGGED1, HES1, and HIF1α, which function to promote tumor cell growth and survival." (PMID 40427168, 2025). "We did not observe a significant correlation between Notch1 mutation in CPS‐high PD‐L1 and tumor‐infiltrating CD8+ T cells." (PMID 41026775, 2025). "Based on these findings, Notch1 and CD10 could be potential therapeutic targets in CRC, used in combination with chemotherapy to limit tumor progression and enhance therapy response." (PMID 40060224, 2025). "If SRCC constitute the major dormant cancer population (or one of them), riboflavin fluorescence (or SLC52A1-3), NOTCH1, and CD82, may serve as reliable markers for the clinical assessment of tumor cell dormancy and prediction of relapse." (PMID 41453945, 2025). "Even though the tumor cells also expressed NOTCH1, there was no upregulation in either the AFX or the PDS group." (PMID 40387567, 2025). "On the other hand, suppressing Notch1 diminishes tumor growth, likely due to its non-canonical functions." (PMID 40399946, 2025). "TMA cohort analysis (cohort I, N = 184) further revealed a positive correlation between YTHDF1 and the NOTCH1 protein (χ2 = 14.44; P = 0.006) in tumor tissues but not in paired normal tissues." (PMID 41423446, 2025). "Additionally, N1ICD overexpression upregulated the EMT marker VIM to a greater extent than N2ICD overexpression, suggesting distinct roles for NOTCH1 and NOTCH2 in regulating EMT and tumor-intrinsic STING expression." (PMID 40627448, 2025). "In addition, we observed a discordant degree of expression between NOTCH1 and HES1 in the same tumor samples." (PMID 40387567, 2025). "Functionally, knockout of NOTCH1 in ESCC cells inhibits endothelial cell migration and tube formation in vitro, reduces microvascular density in subcutaneous tumor xenografts in vivo, and decreases microvascular density in carcinogen-induced ESCC among Notch1-knockout mice." (PMID 40691441, 2025). "By integrating analysis of CUT&Tag and RNA sequencing data, we identified ubiquitin-specific protease 5 (USP5) as a Notch-signaling downstream effector that is transcriptionally upregulated by the NOTCH1 intracellular domain (NICD1)–RBPJ complex and mediates tumor angiogenesis." (PMID 40691441, 2025). "In contrast, for patients with HR-positive/HER2-negative tumours without adjuvant chemotherapy, no impact of NOTCH1 mRNA expression was observed." (PMID 39153127, 2025). "Further investigation was conducted to determine whether the effects of tumor cell CRTC1 on T cell survival and cytotoxic capacity are mediated through the Notch1/Akt signaling pathway." (PMID 40977688, 2025). "Notably, whereas cells in the Notch1 TIC/tumor branch express ectopic NRAS at a level comparable with the OIS cluster, the Dlk1-type TIC/tumor branch shows a much lower NRAS expression." (PMID 40324881, 2025). "The results demonstrated that CTT triggered significant upregulation of NICD in CD4+ T cells compared to that in tumor-bearing controls, which was abrogated by CD8+ T cell depletion after CTT, indicating that CD8+ T cells are indispensable for CTT-induced Notch1 activation in CD4+ T cells." (PMID 40277945, 2025). "Our results suggest that the downregulation of NOTCH1 in SCLC, previously attributed to its tumor suppressor functions, may be a mechanism by which SCLC avoids immune surveillance." (PMID 40627448, 2025). "The direct link we propose between DLK1, NOTCH1 signaling, and ABCB1 expression also suggests that ABCB1 inhibition could improve anti-tumor responses to DLK1-directed ADCs." (PMID 40595495, 2025).
tumor (continued). "We also assessed whether NOTCH1 and HES1 could play a role in tumor progression and metastasis through EMT induction." (PMID 41009728, 2025). "Both in vitro CCK-8 assays for cell proliferation and Ki-67 staining of in vivo xenograft tumors demonstrated that the tumor-suppressive effect of NOTCH1 knockout was not attributable to the effect on cell proliferation." (PMID 40691441, 2025). "Using this cut off value, tumours with high NOTCH1 mRNA expression were more likely HR negative (OR 2.1, 95% CI 1.20–3.77, p = 0.009) and more likely HER2 positive (OR 3.3, 95% CI 1.89–5.61, p < 0.001) than those with low expression." (PMID 39153127, 2025). "The direct link we propose between DLK1, NOTCH1 signaling, and ABCB1 expression also suggest that ABCB1 inhibition could improve anti-tumor responses to DLK1-directed ADCs." (PMID 39416174, 2024). "Whilst studies on GXYTL1 are limited, its role in the NOTCH pathway may be a driving force for subsequent NOTCH1/2 aberrations, resulting in ACC tumor progression." (PMID 39199639, 2024). "By contrast, Dlk1+ cells were detected in all tumours irrespective of time of onset (n = 15) but retained their hepatocytic morphology and were spatially distinct from NOTCH1/nestin+ regions, where Dlk1+ cells tended to exhibit lower NRAS expression." (PMID 39112713, 2024). "Expression of NICD, the nuclear fragment of NOTCH1 that is shown to be downstream of NUMB but also feeds back to NUMB, completely reversed the effect of RAB4A knockdown on the tumor forming ability." (PMID 39463384, 2024). "Treatment with the Notch1 monoclonal antibody bronticuzumab could delay ACC progression and contribute to partial reduction of tumor volume." (PMID 38866828, 2024). "We selected Notch 1 because it was reported to be one of the main drivers of the EMT program in several cancer cells and was up-regulated in H1975 cells when they grow as tumor spheres." (PMID 39430758, 2024). "Similar to NRAS(G12V)-N1ICD-driven tumours, early-onset tumours with DS3–4 were mostly positive for nestin and NOTCH1, whereas the majority of late-onset differentiated tumours (DS1–2) were negative for nestin/NOTCH1." (PMID 39112713, 2024). "Furthermore, the percentage of Notch1+CD8+T cells and PD-1+CD8+T cells within tumor tissues exhibited a greater magnitude than that observed in adjacent normal tissues." (PMID 38650927, 2024). "In our study, the level of NOTCH1 expression in tumor tissue of smokers was lower than in the group of nonsmoking patients, but this observation is difficult to interpret, since the data on the use of NOTCH1 as a predictor of HNSCC outcome are contradictory." (PMID 38540309, 2024). "Previous studies have indicated that aberrant expression of key proteins in the Notch-1 pathway could influence PTEN expression, thereby affecting tumor development." (PMID 38733531, 2024). "Also, groups SeNPs loaded P. crinita extract (25, 50 mg/kg) revealed a more significant decrease in the Notch 1 levels (59.7% and 68.7%), in comparison with untreated SEC-mice (tumor control group)." (PMID 38469406, 2024). "The present study also brought evidence of NLRP7 involvement in the differentiation of tumor cells through the induction of embryonic markers such as NANOG, NOTCH1 and OCT3/4, and the activation of their survival through the induction of genes, such as CD74 and its co-receptor CXCR2." (PMID 36980199, 2023). "However, numerous studies have also shown that NOTCH1 is upregulated in HNSCC tissues compared with adjacent normal tissues and plays positive roles in regulating tumor cell proliferation, EMT, invasion/metastasis, and CSC properties." (PMID 37653021, 2023). "The density of tumors was similar in all three genotypes, arguing Notch1 is not required for tumor initiation." (PMID 36658434, 2023).
tumor (continued). "It is now widely recognized that the MYC transcription factor is a dominant oncogenic driver in a majority of human T-ALL and is often activated downstream of NOTCH1, and targeting the NOTCH/MYC pathway can lead to cell death by increasing the apoptosis of tumor cells." (PMID 36691066, 2023). "The significant prognostic variables for survival were the late-stage TN (III/IV) and Poor tumor differentiation, whereas NOTCH1 expression was not correlated with OSCC mortality." (PMID 37859809, 2023). "In the Notch1 cohort, this appeared to be at the expense of MSCC and AC (NST) phenotypes, whereas in the Notch2 cohort, the AME phenotype tumours were lost, while the MSCC tumours were retained." (PMID 37686600, 2023). "Second, it also co-stimulates Notch1 activation in endothelial cells in the pre-metastatic niche, which induces the expression of cell adhesion molecule VCAM1 and neutrophil infiltration, facilitating the homing of metastasizing tumor cells in the lungs." (PMID 37887354, 2023). "Taken together, these observations suggest that while Notch1 clearly can act as a tumor suppressor in HNSCC, Notch3 has an oncogenic role, is involved in a distinct signaling cascade and contributes to the survival of metastatic derivatives of tumor cells." (PMID 37202533, 2023). "We show that an invasive phenotype of the tumor, stimulated by enteric ETBF infection, is further supported by decreased E-cadherin and increased N-cadherin and vimentin expression, as well as nuclear accumulation of β-catenin and cleaved Notch1." (PMID 37503343, 2023). "Moreover, NOTCH1 and NOTCH2 expression was significantly reduced in cases with residual tumours (R1) (p = 0.03 and p = 0.02, respectively)." (PMID 36982928, 2023). "Our data, however, suggest that the absence of Notch1 or Notch2 tends to accelerate tumor development in BP mice." (PMID 36672468, 2023). "Notch1 has also been reported to act as an important mediator of T cell activity, but its immune anti-tumor effects have not been elucidated." (PMID 37391408, 2023). "In addition, when encountering circulating tumor cells (CTCs), PMN-MDSCs can produce excessive levels of ROS to upregulate Notch1 expression in CTCs via the Nrf-2-ARE axis." (PMID 37646034, 2023). "Given that tumor heterogeneity may influence drug responses of tumor cells, we thus considered whether TRIM22 expression levels could determine the sensitivity of SKCM cells to Notch1 inhibitors." (PMID 37415153, 2023). "Our findings showed that high Notch1 protein level was associated with tumor differentiation, but not with TNM classification, tumor stage and death." (PMID 37859809, 2023). "The expression of inducible nitric oxide synthase in CD24+CD133+ LCSCs, but not CD24−CD133− LCSCs, has been found to promote stemness characteristics of LCSCs via Notch1 signaling, and to accelerate HCC initiation and tumor formation in a mouse xenograft tumor model." (PMID 38009775, 2023). "A significant positive correlation was observed between Notch1 expression and tumor differentiation (P<0.05), but not between Notch1 expression and TNM stage, AJCC stage and Death status (P>0.05)." (PMID 37859809, 2023). "Also, the inhibition of Notch1 facilitates autophagy signaling, which resulted in the inhibition of EMT, and survival signaling to eradicate tumor growth." (PMID 36909163, 2023). "MiR-146a, known for its tumor suppressor function through binding to the 3’ UTRs of EGFR and NOTCH1 mRNA in breast cancer and glioma, was found to present lower levels in HPV+ PC cases compared to those in HPV− PC cases, and to correlate with an expected elevation of EGFR expression." (PMID 38069131, 2023). "Surprisingly, the drug did not exert any effect on tumor growth nor on tumor weight as compared to the vehicle; nevertheless, it inhibited the NOTCH1 pathway." (PMID 35457006, 2022).
tumor (continued). "Unexpectedly, we found that Notch1 did not impact either oncogenic or tumor-suppressive influence in pancreatic tumorigenesis in the context of mutant KRAS and inactivation of p16." (PMID 36970723, 2022). "In order to evaluate whether MET levels are modulated after NOTCH signaling inhibition, we silenced NOTCH1 and NOTCH3, the two NOTCH receptors hyper-activated in our cell tumor context, in two FP-RMS (RH30 and RH4) and two FN-RMS (RD and JR1) cell lines." (PMID 35574376, 2022). "We also asked if restoring Notch1 in CD8+ T-cells, by blocking A2AR, promotes anti-tumor immunity." (PMID 36090975, 2022). "Assessment of engrafted CLL cells showed a moderate, but not significant, increase in the tumor burden of NOTCH1-transduced cells after 3 weeks." (PMID 36266281, 2022). "A small-molecule drug ABT-737 and tumor-suppressive microRNA (miRNA) miR-34a, which are promising candidates for TNBC therapy, were encapsulated in poly(lactic-co-glycolic acid) nanoparticles (NP) and functionalized with Notch-1." (PMID 36017236, 2022). "During EMT, the anti-apoptotic effecter NK-κB activated via the Notch-1 pathway and TGF-β may regulate tumor microenvironment through TGF-β/SMAD signaling." (PMID 35155236, 2022). "Similarly, NOTCH1-mutant HNSCC xenografts treated with PI3K pathway inhibitors demonstrated elevated cell death and significant tumor volume reduction in vivo." (PMID 35887235, 2022). "In endothelial cells, Notch1 ICD activity in human carcinomas and melanoma orchestrated tumor progression and metastasis through increasing expression of chemokines and the adhesion molecule VCAM1, which promotes neutrophil infiltration and tumor cell adhesion." (PMID 35330188, 2022). "Second, tumor-derived exosomes can promote epithelial-to-mesenchymal transition (EMT) and tumor metastasis by activating the resting cancer cells to aggressively metastasize via multiple inducible signaling molecules like Notch1 and HIF1α." (PMID 35757760, 2022). "Indeed, Western blot analysis of tumour lysates indicated decreased Notch 1 levels in 8C7-PBD-treated tumours, with the one outlier being the largest, most resistant tumour." (PMID 35804938, 2022). "Therefore, NOTCH1 activation levels, as negatively regulated by DLK1, appeared critical for the function of this receptor as an oncogenic or as a tumor suppressor protein in MDA-MB-231 cells." (PMID 35163478, 2022). "Notch 1, 2, 3, FBXW7, and other genes serve as tumor suppressor genes in T-ALL and breast cancer." (PMID 35096263, 2022). "NOTCH1 expression is decreased in UBC, suggesting a tumor-suppressive role." (PMID 35073251, 2022). "To identify new effective immunotherapeutic strategies to overcome tumor-induced immunosuppression, here we investigated the immunosuppressive pathway regulating Notch1 downstream of A2AR and strategies to target this pathway to enhance T-cell anti-tumor responses." (PMID 36090975, 2022). "In this study, we found neither biallelic inactivation of Notch1 in the tumor cells nor heterozygous deletion of Notch1 globally exerted a statistically significant impact on pancreatic tumorigenesis driven by oncogenic Kras in the context of p16 inactivation." (PMID 36970723, 2022). "Moreover, depending on the level of inhibition of NOTCH1 activation generated by different levels of DLK2 expression, cell proliferation, cell cycle dynamics, cell apoptosis, cell migration, and tumor growth in vivo were affected in opposite directions." (PMID 35163478, 2022). "As tumor-suppressor genes, the inactivation of FAT1 and NOTCH1 may converge to inhibit the Wnt/β-catenin signaling pathway, which is implicated in the deregulation of cell polarity and differentiation." (PMID 34194478, 2021). "Unlike Notch1, Notch2 has a more substantial role in tumor growth and plays a suppressive role in tumor angiogenesis through PTEN induction and AKT dephosphorylation." (PMID 36643842, 2021).
tumor (continued). "In addition, co-loaded nanoparticles containing doxorubicin and the Notch1-inhibitor miR-34a affected TNBC cell migration more effectively and allowed enhanced tumor growth suppression compared with the drug alone in vitro and in vivo." (PMID 34680255, 2021). "Furthermore, FOXP3 suppression can inhibit tumor invasion and metastasis via downregulating the angiogenic factor VEGF, the epithelial-mesenchymal transition (EMT), and the Notch1/Hes1 pathway." (PMID 37305162, 2021). "Further investigations revealed that several pathways, such as inhibition of the self-renewal of cancer stem cells/tumor-initiating cells through NOTCH1 activation and downregulation of heat shock factor 1 (HSF1), thereby increasing tumor cell apoptosis, are involved in the process." (PMID 34204214, 2021). "Transcription factors like NOTCH1 (16%) and KMT2B (16%), UNC13C (14%), another tumor suppressor, ERCC2 (14%) involved in nucleotide excision repair pathway, were recurrently mutated, whereas genes like CDKN2A, MLH1, FGFR1, EGFR, etc. had a less than 10% mutation frequency." (PMID 34796107, 2021). "We created the Neo-fs index—defined as the number of marker proteins with low expression among the five independent prognosticators (APC, NOTCH1, ARID1A, EYS, and filamin A)—to develop a simple, practical biomarker with potential prognostic or predictive value reflective of tumor biology." (PMID 33801954, 2021). "For example, Notch-1, MMPs, miR-100, LMP1, and HIF alpha promote EMT and tumor metastasis." (PMID 33627627, 2021). "Accordingly, NOTCH1 mRNA expression is reduced in human colorectal mucinous adenocarcinomas, compared with non-mucinous tumours, suggesting a tumour suppressor role for Notch in these human CRC subsets." (PMID 33673710, 2021). "An important issue to be further addressed in the near future is to verify the relevance of the VAV1-dependent tumor suppressor function in VAV2- and VAV3-driven tumors, particularly in those that may be NOTCH1-dependent." (PMID 34571765, 2021). "The results indicate that Notch 1 expression in primary tumor biopsies was significantly correlated with a non-response to regorafenib (p = 0.036)." (PMID 33916610, 2021). "Tspan5 correlation analyses of TCGA tumour samples revealed that Tspan5 expression is positively correlated with the expression of ADAM10, Notch1, Notch2, Notch3, Notch4, Hey1, vimentin, N‐cadherin and Snail, whereas it is negatively correlated with E‐cadherin in HCC tissues." (PMID 33955149, 2021). "For instance, inhibition of Notch1 via the bioactive compound psoralidin or Notch1 silencing blocked the growth of ALDH1+ cells, thus resulting in a low mammosphere formation, increased apoptosis, and limited tumor growth in mice models." (PMID 35582386, 2021). "It is remarkable that down-regulation of Notch1, which occurs as a downstream effect of PrPC silencing, inhibits the PI3K/Akt/mTOR pathway to abolish CSC stemness, self-renewal, invasiveness, and in vivo tumor growth in GBM." (PMID 33418999, 2021). "In addition, the aberrant activation of NOTCH1 in CRC, specifically serrated neoplasia pathway, leads to an increase in Ephrin type-B receptor 4 (EPHB4), which promotes tumor growth and cell migration." (PMID 33478063, 2021). "We first evaluated the expressions of NOTCH1 and DLL4 in UM-UC-1 and SCaBER microtumors using a live single cell biosensor, which was demonstrated in cancer cells, tumor organoids derived from patients, and tumor tissues." (PMID 34831307, 2021). "In addition, the complete NOTCH1 extracellular domain fused to Fc (resulting in a NOTCH1 decoy) strongly impeded primary endothelial cell cultures (HUVEC) sprouting and even inhibited tumour angiogenesis in mice." (PMID 34944837, 2021). "It has been reported that Nrf2 nuclear translocation could activate Notch1/Snail signaling pathway, which accelerated EMT and metastasis of tumor cells." (PMID 34466284, 2021).